IL6 (interleukin 6)
Diseases named in the same sentence as IL6 in open-access papers (continued):
Sharing a sentence is not in itself a finding about the gene and the disease.
adult-onset Still disease (15 papers, 2012 to 2025). A rare inflammatory multisystem disorder characterized clinically by fever of unknown origin, arthralgia or arthritis, hyperleucocytosis, and typical skin rash. "Indeed, secretion of IL-6 by immature neutrophils has been implicated in autoinflammatory diseases such as chronic graft versus host disease and adult-onset Still’s disease." (PMID 38822352, 2024). "Tocilizumab, an IL-6 inhibitor, has been proven effective in patients with adult-onset Still's disease (AOSD)." (PMID 38507702, 2025). "The effectiveness of tocilizumab for other inflammatory conditions with high levels of IL-6, such as adult-onset Still’s disease, may suggest a role for this agent in the treatment of VEXAS syndrome as well." (PMID 36544501, 2022). "Adult-onset Still’s disease (AOSD) is a self-inflammatory disease showing macrophage and neutrophil activation by inflammatory cytokines such as TNF-α, IL-6, and IL-18." (PMID 33627085, 2021). "Here, we present the case of a 56-year-old female with adult onset Still's disease (AOSD) who developed herpes zoster meningitis while being treated with cyclosporin A, prednisolone, and an anti-IL-6 therapeutic, tocilizumab (TCZ)." (PMID 27092286, 2016). "Adult-onset Still’s disease (AOSD) is a self-inflammatory disease exhibiting macrophage and neutrophil activation by inflammatory cytokines such as tumor necrosis factor-α (TNF-α), interleukin-6 (IL-6), and interleukin-18 (IL-18)." (PMID 33627085, 2021). "Among the examined Th17-related cytokines, elevated levels of serum IL-6 and IL-17 were positively correlated with the frequencies of circulating GLK-expressing T-cells and the levels of GLK proteins as well as transcripts in patients with adult-onset Still's disease." (PMID 22867055, 2012).
alcohol abuse (15 papers, 2017 to 2025). The use of alcoholic beverages to excess, either on individual occasions ("binge drinking") or as a regular practice. "Moreover, they found that changes in IL-6 and IL-17A plasma concentrations in alcohol use disorder patients were associated with the presence of liver and pancreatic diseases." (PMID 36830990, 2023). "A recent meta-analysis showed consistent evidence of IL-6 elevation in subjects diagnosed with alcohol use disorder compared to healthy subjects." (PMID 36830990, 2023). "Chronic ethanol exposure in C57BL6/J mice increases pro-inflammatory cytokines in several tissues, including the heart, and clinically, IL6 and IL1β are known to be elevated with alcohol abuse." (PMID 38132102, 2023). "For instance, a recent study found that patients with alcohol use disorders had a significant increase in IL-6 concentrations but a reduction in TNF-α approximately 3 h after acute alcohol ingestion." (PMID 37760011, 2023). "According with our experimental results, human studies have also shown that alcohol abuse during human pregnancy induces upregulation of cytokines (IL-1β, IL-6, and TNF-α) in both maternal blood and fetal cord levels at delivery." (PMID 28738878, 2017). "In addition, BMI at 20 years of age, TNM stage, alcohol abuse and sleep disturbance were no longer associated with IL-6." (PMID 29951282, 2018). "Alcohol abuse can trigger the formation of endotoxins and activate Kupffer cells, thereby generating the pro-inflammatory factors tumor necrosis factor-alpha (TNF-α) and interleukin-6 (IL-6)." (PMID 35685625, 2022). "Indeed, studies on patients with alcohol use disorder have demonstrated a positive correlation between craving for alcohol and levels of pro-inflammatory cytokines (such as TNF-α and IL-6)." (PMID 36009076, 2022).
anorexia nervosa (15 papers, 2015 to 2025). A disorder most often seen in adolescent females characterized by a refusal to maintain a minimally normal body weight, an intense fear of gaining weight, a disturbance in body image, and, in postmenarcheal females, the development of amenorrhea. "Pharmacological modulation of IL-6 signaling through IL-6 blockade may be a potential route of action for diseases or disorders with a significant weight loss component, such as cancer cachexia and anorexia nervosa." (PMID 32878032, 2020). "Modulating IL-6 signaling may be a potential future therapeutic avenue used as an adjunct for the treatment of disorders associated with weight changes, such as cancer cachexia and anorexia nervosa." (PMID 32878032, 2020). "Multiple linear regression analysis with anorexia nervosa, bulimia nervosa and binge eating as dependent variables showed that IL-6 and leptin best explained ED symptoms, even when adjusted for body mass index (BMI)." (PMID 30873471, 2017). "As weight gain appears to be a side-effect of inhibitors of IL-6 signaling, they may be a potential pharmacological adjunct for the treatment of cancer cachexia and anorexia nervosa." (PMID 32878032, 2020). "For example, we previously reported elevated levels of IL-6 in anorexia nervosa patients, suggesting modulating cytokines such as IL-6 could be a possible treatment option for patients with anorexia nervosa." (PMID 32878032, 2020). "Furthermore, patients with anorexia nervosa have elevated levels of proinflammatory cytokines such as interleukin-6 (IL-6) and tumor necrosis factor- (TNF-) alpha." (PMID 26137337, 2015). "Likewise, we did not observe any longitudinal associations between IL-6, restrictive eating behaviours, weight and shape concerns, body dissatisfaction (common phenotypical presentations of anorexia nervosa), or anorexia nervosa." (PMID 32755646, 2020). "Moreover, inflammatory markers such as IL6 or TNFα are enhanced in haemodialysis patients with or without appetite loss, and in anorexia nervosa patients." (PMID 31878925, 2019). "In patients with anorexia nervosa, an increase in pro-inflammatory cytokines, such as interleukin-1β (IL-1β), tumor necrosis factor-α (TNF-α), and interleukin-6 (IL-6), have also been reported." (PMID 35215322, 2022). "Therefore, we propose that, taken together, existing evidence suggests that IL-6 alterations could be a state marker of anorexia nervosa rather than a risk factor for its development." (PMID 32755646, 2020). "Additionally, if IL-6 pathway inhibitors induce weight gain, blocking IL-6 signaling could become a novel adjunct strategy for the treatment of disorders with severely low body weight such as cancer cachexia and anorexia nervosa." (PMID 32878032, 2020). "In univariable models, children in the middle and top third of IL-6 and CRP had greater odds of all diagnoses in adolescence, with the exception of anorexia nervosa in relation to CRP." (PMID 32755646, 2020).
autoimmune encephalitis (15 papers, 2013 to 2025). Inflammation of the brain secondary to an immune response triggered by the body itself. "Autoimmune encephalitis is caused by autoantibodies directed against brain proteins, which activate immune cells and cause the release of inflammatory cytokines like interleukin-6, Il-17, and Il-1β." (PMID 37175665, 2023). "According to recently published research, patients with NMDAR antibody-associated autoimmune encephalitis had increased IL-6, pentraxin-3, CD40L, and IL-17A in their CSF." (PMID 36048783, 2022). "Studies in patients with NMDAR antibody-associated autoimmune encephalitis have shown an increase in serum IL-2 and CSF IL-6, IL-17, CXCL-10, and IL-1β." (PMID 36048783, 2022). "Given that IL-6 has been shown to be elevated in the CSF of many subtypes of AE, it has been therapeutically trialed in several types of autoimmune encephalitis." (PMID 37841263, 2023). "Interleukin-6: IL-6 is thought to play a crucial role in the inflammatory response that occurs in the brain in autoimmune encephalitis." (PMID 37175665, 2023). "The data on CSF cytokine and chemokine profile in autoimmune encephalitis is limited in the literature, and have shown elevation of CSF IL-6 and CXCL13 in previous studies." (PMID 27575749, 2016). "While IL-6 can have protective properties in many infections, its activity seems to be a key in maintaining the chronic inflammation in model of autoimmune encephalitis and various neurological diseases when IL-6 is overexpressed in the central nervous system [reviewed in Ref." (PMID 29163240, 2017). "According to the study, targeting IL-6 with tocilizumab may treat autoimmune encephalitis." (PMID 37175665, 2023).
chronic GVHD (15 papers, 2010 to 2025). "We observed a significant association between the IL6-174 GG genotype of recipients and the occurrence of chronic GVHD." (PMID 34120222, 2022). "We observed a significant increased risk of chronic GVHD in recipients with IL6-597 GG genotype (GG vs. GA vs. AA; P = 0.043)." (PMID 34120222, 2022). "Recipients with the IL6-174 GG genotype developed chronic GVHD more frequently than individuals with the C allele (GG vs. GC/CC; P = 0.049)." (PMID 34120222, 2022). "Contrary to this, we found a significant association between recipients’ IL6-597 GG genotype and the risk of chronic GVHD." (PMID 34120222, 2022). "Similarly, we observed a significant association with an increased risk of chronic GVHD in recipients with IL6-597 GG genotype compared with patients with the other genotypes (GG vs. GA vs. AA; P = 0.043; GG vs. GA/AA; P = 0.012)." (PMID 34120222, 2022). "High levels of IL6 could be associated with more severe forms of chronic GVHD." (PMID 34120222, 2022). "Associated with T lymphocytes, IFNγ and TNFα are core cytokines of chronic GvHD pathogenesis, and IL-6 and IL-22 aggravate skin lesions." (PMID 39131155, 2024). "Our present studies therefore suggest that IL-6 targeting should be further explored as a strategy for prophylaxis or treatment of late acute and chronic GVHD." (PMID 35566660, 2022). "IL6-174 GG homozygous recipients had a more frequent occurrence of chronic GVHD (GG vs. GC/CC; P = 0.049)." (PMID 34120222, 2022). "A total of 49 in the group of recipients’ IL6-597 SNP developed chronic GVHD: 22 of 91 patients (24.2%) with the GG genotype, 8 of 59 patients (13.6%) with the AA genotype and 19 of 149 patients (12.8%) with the GA genotype." (PMID 34120222, 2022). "Studies in mice and humans have indicated that tissue damage releases interleukin-1β and interleukin-6, which induces Th17-cell differentiation, promote the development of chronic GVHD." (PMID 35905125, 2022). "Unfortunately, the design of this study did not include longitudinal samples in the long-term follow-up, preventing us to draw any correlation between IL6 and chronic GvHD." (PMID 31632401, 2019). "IL-1 and IL-6-rich environments in damaged skin later after HSCT may propagate the proinflammatory MΦ bias in chronic GvHD." (PMID 38010706, 2024). "We could not detect any associations between differences in IL-6 signaling and later chronic GVHD." (PMID 35566660, 2022). "Reduction of chronic GVHD was seen upon treatment of the mice with AM80, a retinoid that regulates RAR and IL-6, down-regulating both Th1 and Th17." (PMID 23843069, 2013). "An unselective systemic blockade of IL-6 is probably not without caveats, given the physiological importance of IL-6 in tissue regeneration and homeostasis in both the liver and GI tract, two organs commonly affected both in acute and chronic GVHD." (PMID 28642760, 2017). "These agents suppress key pro-inflammatory cytokines, including interferon-gamma (IFN-γ) and interleukin-6 (IL-6), downregulate antigen-presenting cell (APC) activity, and expand regulatory T cells (Tregs), thereby promoting a tolerogenic immune environment in both acute and chronic GVHD." (PMID 40722603, 2025).
gallstones (15 papers, 2015 to 2025). Solid crystalline precipitates in the biliary tract, usually formed in the gallbladder, resulting in the condition of cholelithiasis. "Interleukin (IL)-6, a kind of cytokine, has been linked to gallstone formation due to its role in promoting inflammation." (PMID 39758317, 2024). "The Western diet has been reported to significantly increase systemic inflammatory biomarkers such as CRP, IL-6, and IL-10, associated with an increased risk of gallstones." (PMID 38765815, 2024). "A study of subjects in China reported an association between levels of IL-6 and IL-10 and the risk of gallstone development." (PMID 38779446, 2024). "Previous studies indicated increased cholesterol levels could induce the expressions of inflammatory factors such as interleukin (IL)-1, IL-6, and tumor necrosis factor-alpha, which could cause cholecystitis and induce the formation of gallstones." (PMID 32011459, 2020). "Lastly, inflammatory mediators released by adipose tissue, such as TNF-α and IL-6, can intensify metabolic dysregulation and abnormal cholesterol metabolism, facilitating gallstone development." (PMID 41287115, 2025). "For example, gallstone patients had higher levels of IL‐6, IL‐10 and IL‐12p70 than population‐based controls, and GBC patients had increased levels of C‐reactive protein (CRP), CCL20, IL‐16, sTNFRI and sTNFRII compared to gallstones controls." (PMID 39482824, 2025). "Higher DII scores are also associated with the production of higher concentrations of TNF-α, IL-6, CRP, and a range of other factors that contribute to greater gallstone risk." (PMID 38779446, 2024). "Given that IL-10 and IL-6 are inflammatory biomarkers related to DII calculations, this supports the existence of a direct association between DII values and gallstone development." (PMID 38779446, 2024). "Studies have revealed that inflammatory biomarkers such as IL-6, IL-8, TNF-α and CRP are associated with an increased risk of gallstones." (PMID 38765815, 2024). "The correlations between IL-4 and IL-6, as well as between IL-6 and IL-7, suggest that the initiated inflammatory response to gallstone induced injury is being actively intensified and sustained through cytokines modulated intercellular signalling pathway." (PMID 34449702, 2021). "It has been revealed that IL-6 elevation in gallbladder tissues is related to inflammation and gallstone formation." (PMID 34449702, 2021). "IL-6 may be an important mediator between the chronic inflammatory state due to gallstones and progression to carcinogenesis." (PMID 33574564, 2021). "As IL-6 role in cholecystitis is stimulation of acute phase protein and albumin synthesis, as well as stimulation of B cells and immunoglobulin production, we speculate that IL-6 is a key interleukin of gallstone wall response to the inflammatory process." (PMID 34449702, 2021). "Gallstones can not only induce cellular stress, but they can also disturb the epithelial barrier, releasing epitheliocyte contents in the extracellular space, thus inducing TNFα and IL-6 expression in immune cells, as well as acute phase protein synthesis by binding to hepatocytes." (PMID 34449702, 2021). "While MTBE significantly increased the serum levels of IL-6, MMP did not in both hamster models of cholesterol and pigmented gallstones." (PMID 31182117, 2019).
gastroesophageal reflux disease (15 papers, 2016 to 2025). A chronic disorder characterized by reflux of the gastric and/or duodenal contents into the distal esophagus. "IL-6, another pro-inflammatory marker, is abundantly present in the oesophageal mucosa of GERD patients; recurrent acid reflux is sufficient to stimulate oesophageal epithelial cells to produce IL-6, leading to esophagitis." (PMID 39203915, 2024). "According to Nam’s study, visceral fat, leptin as well as circulating levels of IL-1 beta and IL-6 were higher in patients with reflux esophagitis than healthy controls." (PMID 34793546, 2021). "And it also shows its therapeutic effect on gastroesophageal reflux disease rats by reducing the levels of pro-inflammatory biomarkers such as IL-1β, IL-6 and TNF-α." (PMID 33841162, 2021). "Previous research has demonstrated that the TNF-α, IL-1β, and IL-6 concentrations increased in the esophageal tissues of rats in several reflux esophagitis models." (PMID 31281769, 2019). "Inflammatory cytokines (interleukin-6, IL-6 and interleukin-8, IL-8), leukocytes, and oxidative stress seem to have an important role in the development of the gastroesophageal reflux disease." (PMID 30103510, 2018). "The patient with the highest IL-6 level (26.3 pg/mL) presented with severe skin sclerosis, ILD, reflux esophagitis, and cytoplasmic antibody patterns (AC-19/20)." (PMID 40843700, 2025). "Alteration in cytokines (IL-1, IL-6, and TNF) levels also triggers gastrointestinal disorders such as gastroesophageal reflux disease (GERD), and inflammatory bowel disorder." (PMID 37163444, 2023). "This activation of the NF-κB pathway is paralleled by a simultaneous increase in interleukin (IL) IL-1β, IL-6, IL-8, and tumor necrosis factor (TNF) along the spectrum of reflux esophagitis, BE, and adenocarcinoma." (PMID 35511379, 2022). "The primary aim of our study was to compare the differences in plasma immunological profiles (TNF- α receptor, IL-6, IFN-γ, IL-12, IL-17, IL-22, and IL-23) of patients with achalasia, eosinophilic esophagitis (EoE), and gastroesophageal reflux disease (GERD)." (PMID 30744559, 2019). "However, the mRNA levels of IL-8, IL-6, MCP-1 and RANTES were not upregulated in heartburn patients regardless the use of PPI versus controls in this study, even though the IL-33 mRNA level in heartburn patients still correlated with IL-8 and IL-6 levels." (PMID 27111066, 2016).